CD44 (CD44 molecule (IN blood group))
Diseases named in the same sentence as CD44 in open-access papers (continued):
Sharing a sentence is not in itself a finding about the gene and the disease.
tumor (continued). "Previous studies indicated that overexpressed CD44 is frequently complexed with HA at the tumor attachment sites, and HA-CD44 interaction stimulates a variety of tumor cell-specific functions and cancer progression." (PMID 27070574, 2016). "In particular, CD44 isoforms originating from alternative splicing are thought to be important in tumour metastasis." (PMID 27074785, 2016). "GRPR+ CD44+ cells in a group of two or three were scattered in the sections confirming the presence of tumour cells." (PMID 27827443, 2016). "CD44 plays an important role in hetero-adhesion and promotes the invasion and metastasis of tumor cells." (PMID 26959747, 2016). "HNSCC tumors show a proportion of CD44+ cells ranging from 0.1% to 41.72% of the tumor population, and when isolated, CD44+ cells also share CSC properties." (PMID 26907349, 2016). "The gene expression profiles of 254 tumor samples from The Cancer Genome Atlas RNAseqV2 were analyzed for the presence of CD44 isoforms." (PMID 27253518, 2016). "Correspondingly, 1 × 104 CD133+CD44+ cells have been sufficient to establish a tumor in a xenograft mouse model." (PMID 27455311, 2016). "CD44, also expressed on cancer stem cells (CSC) in various tumors, is associated with chemoresistance and tumor regrowth following standard therapy." (PMID 27507056, 2016). "Protein expression of CD133 and CD44 in the cancer tissues of the PDX models was in concordance with that in the clinical tumor tissue samples using IHC assay." (PMID 27329727, 2016). "Quantification analysis showed that the densities of CD44+ positive staining were significantly lower in the tumor from the YM155-treated mice than those in tumor tissues from vehicle-treated mice." (PMID 26771139, 2016). "CD44 invariant regulates the redox status, which affects tumor initiation, tumorigenesis, and metastasis." (PMID 26846780, 2016). "HA is known to induce tumor growth and metastasis by interacting with its two main receptors CD44 and RHAMM." (PMID 27595989, 2016). "CD44+ cells can generate new tumors similar to the original tumor when xenografted onto mice, but CD44− cells cannot achieve this." (PMID 27148537, 2016). "CD44 expression was highly correlated with tumor TNM classification (I+II vs. III+IV)(OR 2.38, 95 % CI 1.23–4.60, P = 0.01, fixed-effect)." (PMID 27330410, 2016). "The tumors that developed from the CD44+ cells had identical histology and possessed a diverse group of CD44+ and CD44− cells as seen in the original tumor." (PMID 26907349, 2016). "The fact that CD44 overexpressing tumor cells display the stem cell properties suggests that CD44 is an important cancer stem cell marker." (PMID 27070574, 2016). "FGFR2 KD decreased most GCSC marker expression, including CD44, but increased c-Myc and Sox2 expression and attenuated tumor growth." (PMID 27107424, 2016). "Among the normal-like tumor forming cell lines, the BRCA1-mutated MDA-MB-436 harbored more CD44+/24–/low cells (95 ± 1.4 %) than MDA-MB-231 (90.67 ± 1.75 %)." (PMID 27229859, 2016). "Cells co-expressing CD24 (epithelial marker) and CD44 (mesenchymal marker), CD24hi CD44hi, have been shown to correspond to a hybrid E/M phenotype and possess higher tumour-initiation potential in vitro and in vivo." (PMID 27170649, 2016). "CSC-like cells were independently isolated from CRC cells using CD133, CD44 or EphB2-high as markers and confirmed by tumor sphere formation assay." (PMID 27833077, 2016). "CD44, a glycoprotein found overexpressed on the common types of tumor cell plasma membrane such as lung, colon and breast cancer, and is of particular interest in understanding the HA signaling pathway in tumor development." (PMID 28335277, 2016). "When either population was injected into the peritoneal cavity of mice, only the CD44+ (high claudin-4 expressing tumor cells) exhibited a strong migratory potential." (PMID 27724921, 2016).
tumor (continued). "Members of the CD44 family of transmembrane glycoproteins, in particularly CD44v6 isoforms, were shown to be metastatic determinants of tumor cells, and the expression of several CD44 proteins correlates with aggressive stages of various human cancers." (PMID 27036550, 2016). "CD44 is also the main receptor of the ECM component hyaluronan, and it has been shown that expression of CD44 on tumor cells correlate with cancer cell adhesion to endothelial cells and also with metastasis." (PMID 27411517, 2016). "Vimentin is mainly found in the stroma and CD44 is also found in the tumor stroma, with increased expression close to the tumor epithelium." (PMID 27590006, 2016). "We found that 57.8% (59/101), 71.3% (72/101), and 57.8% (59/101) GC tumour specimens stained positively for CD44, Shh, and Gli1 protein, respectively." (PMID 26839535, 2016). "Interaction of CD44 with its ligand, hyaluronan, will promote tumor growth, strengthen the extravasation and lead to metastasis." (PMID 27521216, 2016). "GAPLINC regulates CD44 as a molecular sponge for miR-211-3p and enhances tumor migration and invasion." (PMID 27729869, 2016). "In our observation we found that CD44 expression was considerably high in recurrant-origin SCC084/R cell line compared to primary tumour-origin SCC131/R cell line." (PMID 27045798, 2016). "A previous study showed that CD44-positive tumor cells have CSC properties, such as self-renewal and tumorigenicity." (PMID 27330410, 2016). "Many early works also found that high expression of CD44 from many types of tumor tissues had a worse impact on survival time in patients." (PMID 27329727, 2016). "We further demonstrated, for the first time, that the hypoxia-induced CSC-sphere formation (by a CD44+ subpopulation) in vitro and tumor metastasis/dissemination in vivo were markedly suppressed by knocking down Id2 expression." (PMID 26965643, 2016). "This allows to regulate Rac1 activity in different manners depending on the cellular process that is controlled by HA/CD44 interaction and is in line with the notion about a dual role of CD44 in tumor cells." (PMID 27163367, 2016). "In the present study, we first evaluated the mRNA expression of 12 CSC-related markers and found the significant differences in the mRNA expression of CD133 and CD44 between clinical HCC tumor tissues and their peritumoral tissues." (PMID 27329727, 2016). "HCCs with microscopic vascular invasion had high mRNA levels of HAPLN1, LGR5, LEF1, SOX9, CD44, Glypican 3 and larger tumor size." (PMID 27191501, 2016). "In parallel, a unique CD44+/β1+ sub-population of tumor cells has been enriched by TME Stimulation, identified by the simultaneous expression of two adhesion molecules, CD44 and the β1 integrin." (PMID 27835603, 2016). "Despite reports that GAPLINC increases GC invasiveness by rescuing CD44 from miR-211, we next examined functional proteins related to tumor growth and invasiveness." (PMID 27729869, 2016). "Our results indicate that Cetuximab alone or in combination with Ixabepilone significantly inhibited tumor growth and reduced CD44+/CD24-/low CSC population in vitro and in vivo." (PMID 26757880, 2016). "We further demonstrated that PGC1α induced MMP2 and CD44 expression and overexpression of PGC1α restored aggressive phenotype of tumor cells suppressed by grifolin." (PMID 27626695, 2016). "Further, mRNA and protein expression analysis of tumor samples also express the markers for stemness like klf4, oct3/4, CD44 and nanog as well as the differentiation marker α-fetoprotein." (PMID 26873175, 2016). "The highest proportion of CD24+/CD44+/EpCAM+/CD133+ cells was detected in the cell line derived from the tumor of a patient with the shortest survival." (PMID 27414409, 2016).
tumor (continued). "Tumor growth was significantly inhibited in the mice injected with the CD117+CD44+-shHOTAIR compared with the mice injected with the CD117+CD44+-scramble, and the tumor volume was significantly reduced in the former (p<0.01)." (PMID 25792974, 2015). "Matrix metalloproteinase (MMP) is a type of extracellular proteinase that binds to integrins or to CD44 to regulate the tumor microenvironment." (PMID 26202311, 2015). "Treatment with PI3K inhibitor LY294002 reduced sphere formation while the dual PI3K/mTOR inhibitor NVP-BEZ235 reduced the CD133/AC141+CD44+ cell population in vivo and subsequently delayed tumor formation." (PMID 25595909, 2015). "Early observations have demonstrated a significant correlation between CD44 and tumor recurrence and mortality." (PMID 26124179, 2015). "Tumor-sphere assays and in vivo tumor assays were performed to investigate the role of CD44+ cells as TISCs." (PMID 25886575, 2015). "We conclude that CD44+ cells generate the relapsing tumor and, as such, are themselves promising therapeutic targets for treating patients with recurrent PDAC." (PMID 25797268, 2015). "Research on ezrin, CD44, and VEGF and their correlation with tumor prognosis will help to further reveal the underlying mechanism of the invasion and metastasis of GCTB and prognosis of GCTB patients." (PMID 25929323, 2015). "Some authors have found that, in cancer cells undergoing EMT, CD44 mediates the adaption to a relatively high level of intracellular ROS, thus contributing to metastasis formation and drug resistance in tumor cells." (PMID 26064420, 2015). "CD44− C3A-iCSCs comparing with CD44+ C3A-iCSCs displayed higher level of stemness and increased tumor cellular differentiation after xenografts in mice." (PMID 26540347, 2015). "Other markers, such as CD44, are broadly expressed on tumor cells and also in other cell types (for example, leukocytes) present in the same organ sites." (PMID 25886184, 2015). "In the most well-known interaction, CD44 acts as a cell surface receptor for HA (hyaluronic acid), which is closely related to the invasion and metastasis of tumor cells." (PMID 26408312, 2015). "Multivalent interaction of HA with CD44 collaborates in driving numerous tumor-promoting signaling pathways and transporter activities." (PMID 26448753, 2015). "Knockdown of CD44 increases cell compliance, enhances migration potential, facilitates tumor growth and promotes lung metastasis." (PMID 26572077, 2015). "CD44-mediated localization of MMP-9 on tumor cells can regulate tumor cell motility, growth factor activation, and survival mechanisms." (PMID 25999946, 2015). "CD44 clusters facilitate cell binding and internalization of HA thus enabling invasion from tumor masses into the surrounding ECM." (PMID 26029216, 2015). "We noted that CD8+ T cells following bortezomib treatment in tumor-bearing mice maintained expression of CD44, a late T cell activation marker indicative of effector-memory T cells." (PMID 26431276, 2015). "CD44 is a kind of cell adhesion factors, and changes in its expression are related to the progression, invasion, and metastasis of tumors and tumor-free survival rate of patients." (PMID 25929323, 2015). "Interestingly, the dual functions of CD44 exist in cancer where tissue-specific expression of specific variant isoforms of CD44v appears to control progression of some cancers, and these isoforms regulate tumor-initiating cells in sub populations of cancer cells." (PMID 25999946, 2015). "Integrating this experimental and clinical data therefore provides important and novel insights into the role and importance of CD44 in enhancing the efficiency of later stages of tumor dissemination." (PMID 25888636, 2015). "Eμ-TCL1 tg CD44−/− mice displayed a reduced peripheral blood tumor load at 12 months and significantly reduced spleen weights compared to Eμ-TCL1 tg CD44+/+ mice." (PMID 25941526, 2015).
tumor (continued). "The results demonstrated that the HOTAIR expression in clinical EOC tissues and SKOV3 CD117+CD44+CSCs was higher than in SKOV3 tumor tissues and non-CD117+CD44+CSCs." (PMID 25792974, 2015). "Since CD44s and CD44v isoforms are involved in tumor progression and metastasis alternative splicing of CD44 seems to be a decisive event controlling the progression of cancer." (PMID 25904917, 2015). "They demonstrated that CD44+/CD24− tumor cells resembled normal stem/progenitor cells with respect to their ability to self-renew, proliferate, and differentiate." (PMID 25429827, 2015). "The inhibition of CD44 mRNA expression by inducing the expression of siRNA/shRNA in tumor cells is an alternative approach to the use of CD44-blocking antibodies to interfere with the function of CD44 proteins." (PMID 25999946, 2015). "Some other studies have since confirmed that overexpression of this particular isoform of CD44 in different tumour cell systems promotes c-Met function and is involved in the crosstalk between c-Met and the NF-κB or the TGF-β1 signalling pathways." (PMID 28536399, 2015). "In agreement with this, we found that reduced expression of CD44 on vasculogenic tumor cells interfered with their vasculogenic network assembly." (PMID 26189059, 2015). "Secondly, targeting CD44 would attenuate tumor angiogenesis, thus decreasing blood and nutrient supply to the tumor cells." (PMID 26189059, 2015). "CD44 has exhibited positive correlations with tumor recurrence, high-grade SCCs, and poor prognosis." (PMID 26626427, 2015). "High baseline tumor cell CD44 expression in MOC2 was significantly reduced with PD901 but enhanced (by mean fluorescence intensity, MFI) with rapamycin treatment." (PMID 26506415, 2015). "In MDA-MB-435s, we found that silencing CD44 caused a decrease in KLF4 expression, which is required for the maintenance of the stem cell-like features of tumor initiating cells." (PMID 25605020, 2015). "Although the expression of the c-Met co-receptor CD44 was high in all MB tumor samples analyzed, its role in MB is unclear and further studies will also be needed here to reveal c-Met-related and un-related effects of CD44 in MB pathogenesis." (PMID 25625039, 2015). "Adhesion assays were performed to characterize the relationship of HA-induced signaling events to the CD44- and integrin-promoted adhesion of tumor cells to BMECs and Fibronectin." (PMID 26447611, 2015). "Altogether, our results demonstrate that NGF-induced tyrosine kinase independent TrkA signaling through CD44 was sufficient to maintain tumor aggressiveness." (PMID 25840418, 2015). "In a similar approach of using virtual lymph nodes, the effects of CD44 vaccination on tumor growth and lung metastasis were evaluated in a mouse mammary adenocarcinoma model (DA3 cells)." (PMID 25954275, 2015). "As also shown by immunohistochemistry, tumor cells expressed ample amounts of CD44 on their surface." (PMID 25885552, 2015). "In particular this review describes how the glycosaminoglycan hyaluronan (HA) and its major receptor CD44 impact invasive behavior of tumor cells, and provides useful insight when designing new therapeutic strategies in the treatment of cancer." (PMID 26448753, 2015). "Greater understanding of the functions of CD44 isoforms at the molecular level and identification of specific CD44 isoforms on CSCs will, then, allow new strategies to be directed more discerningly against tumor cells." (PMID 26569327, 2015). "Animals injected with PanD3 cells (containing 9.3% of CD95+, 17.8% CD24+ and 23.6% CD44+ cells) developed tumours that were manually detectable 3 months after the injection." (PMID 25613377, 2015). "Although the importance of CD44 in tumor progression and TISC populations has been demonstrated, most reports that define TISC populations with CD44 utilize antibodies that recognizes all CD44 isoforms." (PMID 25886575, 2015).
tumor (continued). "CD44 can also react with other molecules, including collagen, fibronectin, osteopontin, growth factors, and MMPs in tumor cells, but the functional roles of such interactions are less well known." (PMID 25999946, 2015). "In this regard, we recently reported that following a standard chemotherapy for PDAC, a heterogeneous subpopulation of CD44+ cells proliferates and is responsible for tumor recurrence, as shown by almost all recurrent tumor cells becoming CD44+." (PMID 26244163, 2015). "To investigate the role of CSCs markers in TNBC cancerogenesis and tumor progression, we selected 160 TNBCs samples on which we detected protein expression of CD44, CD24, CD133, ALDH1, and ABCG2 by immunohistochemistry." (PMID 26504780, 2015). "The higher tumor-initiating capacity of CD44+ LAPC9 cells was corroborated in an independent orthotopic LDA experiment." (PMID 26246472, 2015). "Overexpression of sol-CD44 displaces exogenous HA from its binding to CD44 and thereby retards tumor cell growth both in vitro and in vivo, and sensitizes tumor cells to chemotherapeutic drugs." (PMID 25999946, 2015). "The blocking antibody induced a shift in the cell-bound fluorescent signal as compared to the cells incubated with the bioconjugate only, thus demonstrating the pivotal role of CD44 in the interaction of the hyaluronan-based bioconjugate with tumor cells." (PMID 26097871, 2015). "This confirms our earlier studies on the CD44-dependent effect of FKBPL on migration of tumor and endothelial cells, further strengthening the role of zCd44 as zFkbpl’s extracellular membrane target." (PMID 25767277, 2015). "CD44+ cells have been reported to be involved in the recurrence of several tumor types including PDACs after radiotherapy." (PMID 25797268, 2015). "To assess the effect of the down-regulation of HOTAIR in CD117+CD44+-shHOTAIR on tumor metastasis, we used H&E staining to detect if there was tumor cell metastasis in the lung tissues." (PMID 25792974, 2015). "There was also a close negative correlation between NDRG1 and nuclear β-catenin and also NDRG1 and CD44 expression in CRC patients with tumor invasion and metastasis to lymph nodes." (PMID 26418878, 2015). "CD44 signaling has been shown to be important in cancer metastasis and tumor growth, but can be broken down into two primary areas." (PMID 25954275, 2015). "CD49f expression is high in mammary stem cells and tumor initiating cells, whereas CD44+ cells fail to show increased tumor formation in a limiting dilution assay in this model." (PMID 25970777, 2015). "Decades of research have shown that CD44 participates in major oncogenic signaling networks and in complexes with oncogenes that promote every aspect of tumor progression." (PMID 25999946, 2015). "CD44 also induces attributes of cells that have undergone an epithelial-mesenchymal transition, leading to tumor metastasis, and resulting in a worse prognosis for colon cancer." (PMID 26079799, 2015). "CD44 cDNA or targeting of CD44-expressing cells has been used to generate tumor immunity in experimental models." (PMID 25954275, 2015). "We found CD44 mainly located in nuclear region and was responsible for the poorly differentiated highly malignant tumor cells by maintenance of low stenmness state." (PMID 26540347, 2015). "Since CD44 is overexpressed in a variety of tumor cells, HA-coated self-assembling nanoparticles or liposomes have been tested for the delivery of siRNAs and/or chemotherapy drugs in pre-clinical xenograft models." (PMID 25954275, 2015). "As discussed in Section “Targeting with Anti-CD44 Antibodies,” the anti-CD44v6 antibody conjugated with mertansine showed dose limiting skin toxicity due to CD44v6 expression in non-tumor skin tissue." (PMID 25999946, 2015). "In another study, chondroitin sulfate E fragments enhanced CD44 cleavage and tumor cell motility upon degradation." (PMID 26029216, 2015).